TNC (tenascin C)
Diseases named in the same sentence as TNC in open-access papers (continued):
Sharing a sentence is not in itself a finding about the gene and the disease.
cancer (continued). "TNC and POSTN were demonstrated to regulate key signaling pathways involved in the maintenance of cancer stem cell features and activity of Wnt and Notch pathways." (PMID 22405133, 2012). "In addition to known Stat3 transcriptional targets (Twist, Snail, Tenascin-C and IL-8), we identified ENPP2 as a novel Stat3 regulated gene, which encodes autotaxin (ATX), a secreted lysophospholipase which mediates mammary tumorigenesis and cancer cell migration." (PMID 22140473, 2011). "Of particular interest, tenascin-C (TNC) is one of the four types that is highly upregulated after changes in tissue organization structure, such as embryogenesis, inflammation, tissue repair, regeneration, or cancer invasion." (PMID 40227326, 2025). "Tenascin-C (TNC) is a large hexametric extracellular matrix glycoprotein that is sparsely expressed in normal tissue but transiently expressed at specific sites during inflammation, wound healing, and cancer invasion." (PMID 39329927, 2024). "TNC promotes EMT and relevant pathways in several types of cancer." (PMID 39273015, 2024). "TNC is an important extracellular matrix protein involved in EMT and cancer progression." (PMID 38245587, 2024). "Interestingly, we also observed that the expression of CDH2, SPP1, TNC, CYR61, SERPINA1, and IL6 correlated with the progression of individual cancer stages." (PMID 37887075, 2023). "A previous study has confirmed that MET facilitates stromal rewiring by upregulating tenascin-C (TNC) expression, which interacts with ECM components and is deeply involved in the metastasis of cancer, stimulating the proliferation and restraining the differentiation of CSCs in PC." (PMID 37727377, 2023). "TFPI, TNC, and ELK3 are less studied in OV, but have been well researched in other cancer." (PMID 37759229, 2023). "TNC is a large ECM glycoprotein, which is known to show restricted expression in adult tissue, but is expressed during embryogenesis, wound healing, chronic inflammation and cancer." (PMID 37098922, 2023). "Thus, TNC appears to have a cell- and context-dependent effect on YAP/TAZ and MKL1 signaling that should be taken into account for anti-cancer therapy." (PMID 36102918, 2022). "Tenascin C (TNC), a secreted glycoprotein that binds to a variety of ECM proteins, such as periostin, fibronectin, integrins, and collagens, is overexpressed in several pathological conditions, including inflammation, wound healing, and cancer." (PMID 34200480, 2021). "Nevertheless, THBS1, FN1, TNC, COL1, and COL4 were expressed in both stroma and cancer cells." (PMID 34121340, 2021). "Histologically positive lymph nodes from four of the patients showed strong stromal tenascin-C expression, and all cancer cells appeared to be negative for tenascin-C." (PMID 34564696, 2021). "Tenascin C is a glycoprotein expressed in connective tissues and neural crest cells, but it’s found upregulated in several cancers with a negative link with prognosis." (PMID 31963820, 2020). "However, periostin and tenascin-C should be mentioned here, as they represent the hot topic of ECM research in cancer biology." (PMID 30925774, 2019). "Tenascin C, a glycoprotein of the ECM, is highly expressed by CAFs and most malignant solid tumors and affects cancer cell migration and metastasis, which leads to poor clinical outcome in cancer patients." (PMID 31137693, 2019). "Tenascin-C is a large extracellular glycoprotein not expressed under physiological conditions, but overexpressed in cancer." (PMID 29515769, 2018). "In particular, CAFs provide potentially oncogenic signals; CAF-derived tenascin-C and TGF-β participate in the acceleration of cancer cell invasion, and CAF-derived growth factors and angiogenic factor VEGF can stimulate cancer progression, including angiogenesis." (PMID 29614830, 2018).
cancer (continued). "The results from in vitro experiments suggest that TNC and TNIIIA2 induce cancer cell invasion with producing MMP and might be related to the cell growth factor of mesenchymal cells and the induction of cytokine production." (PMID 28106752, 2017). "Although it is not clear how TNC or TNIIIA2 participate in cancer invasion, fibroblastic cells have been reported to be involved in the process." (PMID 28106752, 2017). "The 5-year OS and DFS rates in the cancer cell-Tenascin-C-positive group (39.7% and 35.6%, respectively) were also significantly lower than those of the cancer cell-Tenascin-C-negative group (68.3% and 57.1%, respectively; OS: p = 0.001; DFS: p = 0.003)." (PMID 26731558, 2016). "Aptamers against cell surface receptors like human tenascin-C (TN-C), Human epidermal growth factor receptor-3 (HER-3), prostate-specific membrane antigen (PSMA), and many other receptors were successfully generated for cancer diagnosis and therapy." (PMID 28536411, 2015). "Even though significant, the induction of tenascin-C was minimal compared to 18-fold upregulation for Adamts16 or 10-fold upregulation for Lox, both of which are enzymes involved in extracellular matrix (ECM) remodeling and cancer progression." (PMID 24495796, 2014). "This metastatic colonisation by cancer cells largely depends on the support provided by the stromal niche, which is created by a unique composition of local stromal environmental factors including ECM periostin (POSTN) and tenascin-C (TN-C) proteins." (PMID 24216702, 2013). "The interplay between TNC, endothelin receptor type A (EDNRA), integrin α5β1, fibronectin, syndecan-4, and tropomyosin 1 has been reported to particularly contribute to TNC-induced cell proliferation in cancer via the activation of various signaling pathways." (PMID 22481923, 2012). "Finally, we evaluated the expression of hub genes with the development of one of the main complications of IPF patients, LUAD and LUSC, and observed that six of them (CDH2, SPP1, TNC, CYR61, SERPINA1, and IL6) were correlated with the progression of different cancer stages." (PMID 37887075, 2023). "Studies with mice lacking the TNC protein have been instrumental in revealing that high TNC levels enhance pathological phenotypes, such as chronic inflammation (e.g. of the joints), fibrosis (e.g. in the kidney) and cancer." (PMID 36102918, 2022). "Cluster LM3 included multiple focal adhesion genes including collagens, laminins, integrins, and Tenascin C (TNC), which plays an important role in the development and regeneration of articular cartilage and whose interaction with integrins has been widely studied in cancer." (PMID 35820911, 2022). "Tenascin C is a multi-functional ECM glycoprotein able to regulate cell behavior and matrix organization while remodeling, contributing to the formation of both reactive and replacement fibrosis, and it promotes epithelial–mesenchymal transition (EMT), proliferation, and migration of cancer cells." (PMID 34200480, 2021). "For instance, it is unclear whether TnC, TnI and TnT function within the ternary complex (as in the muscle sarcomere) and/or with non-troponin proteins in cancer cells, or function independently as individual subunits/proteolytic fragments." (PMID 29416706, 2018). "We find that JNK signaling, that is active in a subpopulation of cancer cells within tumors, induces a stem cell and wound healing gene expression program that includes a number of extracellular matrix (ECM) proteins such as osteopontin (SPP1) and tenascin C (TNC)." (PMID 30190333, 2018). "Therefore, PRDM14, like tenascin C, may be required for CSC plasticity and the formation of tumorsphere initiating cells, leading to more aggressive cancer phenotypes." (PMID 28423353, 2017).
cancer (continued). "Some aptamers against cancer-related proteins, such as platelet-derived growth factor, vascular endothelial growth factor (VEGF), human epidermal growth factor receptor 2, nuclear factor κB, tenascin-C and prostate-specific membrane antigen, have also been selected." (PMID 22520654, 2012). "Since this active sequence resides within the cancer-associated alternative splicing domain—fibronectin type III repeat A2 (FNIII-A2)–of the TNC molecule, it is presumed that the β1-integrin activation induced by TNIIIA2-containing TNC peptides/fragments may contribute to the pathogenesis of cancer." (PMID 31195598, 2019). "Because tenascin-C is highly expressed in GBM and its expression levels closely correlate with a poor prognosis in GBM patients, it has long been considered to be a negative prognostic factor in cancers including GBM." (PMID 31261783, 2019).
infection (21 papers, 2012 to 2024). The state of being infected such as from the introduction of a foreign agent such as serum, vaccine, antigenic substance or organism. "In accordance with the RNA-seq and qRT-PCR data, deletion of ALKBH5 decreased NLRP12, while increased TNC protein expression in neutrophils during the early stage of infection." (PMID 35764614, 2022). "TNC+/+ C57Bl/6 mice infected with Klebsiella pneumoniae presented with elevated pulmonary TNC protein levels 42 h following infection, and comparably higher local immune response compared to TNC−/− C57Bl/6 mice." (PMID 35778475, 2022). "Infection with MRSA via the airways resulted in enhanced TNC mRNA levels in lungs of TNC+/+ mice at 6 h (P = 0.01 versus naive mice)." (PMID 34319124, 2021). "At 6 h after infection, TNC−/− mice showed significantly more severe tissue pathology compared to TNC+/+ mice (P = 0.013)." (PMID 34319124, 2021). "In contrast, TNC protein expression was detected in the lung tissue particularly at 24 and 48 h after infection." (PMID 34319124, 2021). "To this end, we scored lung tissue slides prepared from TNC+/+ and TNC−/− mice 24 and 42 h after induction of infection." (PMID 33776992, 2021). "Pulmonary TNC protein levels were elevated 42 h after infection in TNC+/+ mice and remained undetectable in TNC−/− mice." (PMID 33776992, 2021). "Tenascin-C (TNC) is an extracellular matrix protein rapidly induced at the site of infection or injury, where it triggers inflammation by activating TLR4 in different cells, including macrophages." (PMID 32209460, 2020). "RV can promote the deposition of extracellular matrix (ECM) proteins, with tenascin-C (TN-C) mRNA expression enhanced in nasal cells following infection." (PMID 31497021, 2019). "However, we observed an increase in TNC protein levels only during the latest stages of infection, when both tissue injury and inflammation have become systemic." (PMID 33776992, 2021). "Little or no expression of TNC was detected in normal adult tissues, but it is overexpressed in embryonic tissues, or injured tissues caused by inflammation, infection, or tumorigenesis." (PMID 27191989, 2016). "Tenascin-C is a hexameric ECM glycoprotein with immediately increased expression in injury and infection." (PMID 36294311, 2022). "Tenascin-C (TN-C), an extracellular matrix (ECM) glycoprotein, is specifically induced upon tissue injury and infection and during septic conditions." (PMID 26557739, 2015). "While pulmonary TNC protein levels increased at the latest stages of infection, histological staining did not reveal the source of this protein." (PMID 33776992, 2021). "Staining lung tissue for TNC confirmed the presence of TNC protein in the pulmonary extracellular matrix of TNC+/+ mice after infection, while TNC−/− tissue remained negative." (PMID 33776992, 2021). "In addition, TNC−/− mice showed more severe pulmonary pathology at 6, but not at 24 or 48 h, after infection." (PMID 34319124, 2021). "Thus, tenascin-C can also play an important role in preventing infection through pathways independent of the traditional innate and adaptive immune systems." (PMID 33912190, 2021). "In another example, it was found that in both asthmatic and non-asthmatic primary bronchial epithelial cells (PBECs), infection with either of two serotypes of human rhinovirus (RV) induced the extracellular release of tenascin-c (TN-C) in a cell death-independent manner." (PMID 32528954, 2020).
cardiovascular diseases (14 papers, 2011 to 2025). "Most studies evaluating the applicability of fetal variants of cell adhesion molecules in cardiovascular diseases have investigated serum levels of different tenascin-C splicing variants." (PMID 27635109, 2016). "Tenascin C is increased in various cardiovascular diseases, and closely linked to tissue injury and inflammation." (PMID 26171980, 2015). "Recent reports have suggested that tenascin-C is expressed in association with the development of cardiovascular diseases, and it may accelerate or sustain fibrosis in cardiovascular tissues." (PMID 27479126, 2016). "Some studies have shown that TNC expression is upregulated in patients with cardiovascular diseases." (PMID 40564778, 2025). "Tenascin-C (TnC) and thrombospondin-1 (TSP-1) have both been implicated in the pathogenesis, diagnosis, and prognosis of patients with cardiovascular disease." (PMID 41010873, 2025). "Tenascin-C, an extracellular matrix glycoprotein, is involved in a number of biological processes that have been linked to AD including inflammation and angiogenesis, which may provide a biological mechanism linking AD to a broad spectrum of cardiovascular diseases and risk factors." (PMID 22163278, 2011). "We hypothesize that SB, particularly severe SB, leads to changes in the concentration of TSP-1 and TnC in human serum, thus providing a new explanation for its connection to cardiovascular diseases, and further cementing the relationship between the two." (PMID 41010873, 2025). "Tenascin-C (TnC) and thrombospondin-1 (TSP-1) are involved in the pathogenesis of cardiovascular disease." (PMID 41010873, 2025).
heart diseases (9 papers, 2012 to 2025). "A mass spectral peak of peptide in our study showed that peptide fragments such as mitogen-activated protein kinase (MAPK), kallikrein related peptidase (KLK), and tenascin-C (TN-C) appeared in the heart disease progression group (group B)." (PMID 35127880, 2021). "TNC may be a feasible diagnostic biomarker and target for the molecular imaging of inflammation because of its specific expression associated with inflammation, which may contribute to the stratification of patients with heart diseases and the selection of appropriate therapy." (PMID 34072423, 2021). "We demonstrate engineering TnC can specifically and precisely modulate cardiac contractility that when combined with gene therapy can be employed as a therapeutic strategy for heart disease." (PMID 26908229, 2016). "TnC has been extensively studied due to its critical involvement with heart function and failure, and has been marked as a therapeutic target in heart disease and other disorders." (PMID 26505480, 2015). "In this study, we examined the effects of cardiac disease-related TnI and TnT modifications on the Ca2+ binding properties of TnC in the Tn complex and on the thin filament." (PMID 22675533, 2012). "Hence, we are able to customize a variety of TnC sensors to tune the contractile response of various cardiac diseases." (PMID 26908229, 2016). "The Ca2+ sensitivity of TnC can be modulated by multiple factors, including its interactions with other myofilament proteins, post-translational modifications of the myofilament, as well as cardiac disease-related protein modifications." (PMID 22675533, 2012). "TNC could be an attractive target for the therapy of certain diseases, and the antigen-binding or single-chain Fv fragments derived from anti-TNC mAbs have been evaluated in heart diseases." (PMID 29065446, 2017).
adenocarcinoma (6 papers, 2014 to 2024). A common cancer characterized by the presence of malignant glandular cells. "Fibronectin showed a similar pattern of upregulation as tenascin-C in adenocarcinoma samples." (PMID 28978001, 2017). "Stromal expression of both tenascin-C and fibronectin was highest in adenocarcinoma." (PMID 28978001, 2017). "We have tested Pax5 motif in our cell lines and found that its target genes such as TNC or DAB1, which are highly expressed in NE-like cells, have increased promoter chromatin accessibility and histone acetylation compared to adenocarcinoma cells." (PMID 38168280, 2023).
musculoskeletal diseases (3 papers, 2012 to 2023). "In cohorts of people with different inflammatory and musculoskeletal diseases, levels of splice-specific tenascin-C variants were lower than and distributed differently from total tenascin-C." (PMID 38077374, 2023). "Using this assay in a cohort of patients with inflammatory and musculoskeletal diseases, we observe differences in the distribution and levels of total tenascin-C compared to tenascin-C variants that raise intriguing questions about the role of distinct proteoforms in inflammatory disease." (PMID 38077374, 2023).
neurodegenerative disease (3 papers, 2014 to 2025). A disorder of the central nervous system characterized by gradual and progressive loss of neural tissue and neurologic function. "TNC gene, which encodes an extracellular matrix protein, is abnormally expressed in neurodegenerative diseases, especially AD and PD, potentially worsening pathology by affecting cell adhesion and inflammation." (PMID 40520613, 2025). "Of the shared proteins, phosphoserine aminotransferase 1 (PSAT1) and TNC (tenascin-C) were shared between AD and FXTAS, ring finger protein 214 (RNF214) was shared between PD and FXTAS, and only PSAT1 was shared between all three neurodegenerative diseases." (PMID 33585555, 2020).
prostate (3 papers, 2016 to 2023). "As a member of the ECM, TNC is abnormally expressed in the process of prostate tumorigenesis, which can promote an increase in microvessel density and is related to proliferation, angiogenesis, adhesion, invasion, and other processes of PCa cells." (PMID 37251946, 2023).
metabolic disorder (2 papers, 2023 to 2024). "Cd and Pb interfere with the normal function of calcium ions in cells, particularly affecting calcium-dependent proteins like TnC, disrupting intracellular metabolism and muscle fiber function, which may lead to metabolic disorders and toxic effects." (PMID 38161700, 2023).
brain) disease (1 paper, 2018). "In exploratory analyses, we found associations of ADAMTS13 activity with levels of VEGF, MMP-3, Tenascin-C, and TIMP-1, which might indeed indicate involvement in vascular remodelling, and in any case encourage further study of ADAMTS13 in relation to vascular (brain) disease and neurodegeneration." (PMID 29615758, 2018).
TNC also shares sentences with these, for which no sentence is quoted: Hypertension (4 papers); idiopathic pulmonary fibrosis (4); Autoimmunity (3); inflammation (3); astrocytic tumor (2); cardiac hypertrophy (2); chronic obstructive pulmonary disease (2); diabetic retinopathy (2); head and neck tumor (2); pancreas carcinomas (2); pulmonary hypertension (2); renal cell carcinoma (2); rotator cuff tears (2); systemic inflammatory response syndrome (2); vasculitis (2); Abdominal obesity (1); acute lung injury (1); acute lymphoblastic leukemia (1); acute myocardial infarction (1); acute myocarditis (1); advanced heart failure (1); age-related macular degeneration (1); Airway obstruction (1); allergies (1); anaplastic astrocytoma (1); anaplastic large cell lymphoma (1); Anaplastic Thyroid Cancer (1); aortic aneurysm (1); asbestosis (1); atopic dermatitis (1).
A further 99 diseases each share a sentence with TNC in 1 paper.